INS (insulin)
Diseases named in the same sentence as INS in open-access papers (continued):
Sharing a sentence is not in itself a finding about the gene and the disease.
Hyperglycemia (continued). "HFD is associated with hyperinsulinemia in mice, and exposure to the low dose STZ treatment destroys a proportion of the β-cells leading to a decrease in insulin production and the development of overt hyperglycaemia." (PMID 25759824, 2015). "At 48 hrs, the newborn insulin-producing cells seemed insufficient to control the blood glucose level as the animals maintained severe hyperglycemia, which probably resulted in the disappearance of regenerated beta-cells." (PMID 26129776, 2015). "In the diabetic state, hyperglycemia per se and subsequent induction of oxidative stress decrease insulin biosynthesis and secretion and finally bring about apoptosis." (PMID 25794287, 2015). "Persons with a low ratio (<1.3), suggestive of overall hyperglycemia, responded better to twice daily insulin." (PMID 25874190, 2015). "Patients are characterized by severe progressive hyperglycemia and beta-cell dysfunction, with impaired glucose-stimulated insulin secretion response by pancreatic beta-cells in contrast to insulin resistance by target tissues displayed by most NIDDM patients." (PMID 27551471, 2015). "Increased plasma insulin levels, can correct hyperglycemia not only in Type 1 but also in Type 2 diabetic patients." (PMID 25647228, 2015). "Rapamycin has the potential to improve insulin signaling and reduce lipid accumulation in the liver induced by chronic low-grade systemic inflammation, but it also has a negative effect on β-cell function and hepatic gluconeogenesis, which may cause hyperglycemia." (PMID 26449763, 2015). "KO mice demonstrate greater hyperglycemia and impaired glucose tolerance but lower insulin levels on HFD compared to WT." (PMID 26047815, 2015). "PKCα is suggested to play a role in insulin granule recruitment for exocytosis and insulin secretion in response to glucose, and its expression is found to be modulated by hyperglycaemia." (PMID 26398746, 2015). "Palmitoleic acid has been reported to improve hepatic lipid metabolism and attenuate hyperglycemia and hypertriglyceridemia by increasing insulin sensitivity." (PMID 26176541, 2015). "The amount of glucose infused to maintain hyperglycemia decreased between 3h and 5h of infusion, indicating the existence of whole-body insulin resistance at 5h." (PMID 25798922, 2015). "Intravenous Insulin therapy is considered the best approach for managing hyperglycemia in critical patients but once patient starts oral feeds bolus insulin is required and therefore it is essential to switch the patients to subcutaneous insulin therapy." (PMID 25874191, 2015). "DM is a metabolic disease characterized by hyperglycemia resulting from progressive defects in insulin secretion and action." (PMID 26089953, 2015). "In sum, PPP2R5C HepKD in diabetic mice worsened their dyslipidemia but ameliorated their hyperglycemia and improved their insulin response." (PMID 26440364, 2015). "In insulin-resistant people who consume high GI foods, the postprandial hyperglycaemia and insulinaemia are magnified, likely contributing to β-cell exhaustion and the development of T2DM." (PMID 25774705, 2015). "Diabetes mellitus is a metabolic disorder characterized by hyperglycemia resulting from insufficient secretion of or receptor insensitivity to endogenous insulin." (PMID 25763088, 2015). "ADMSC transplantation promoted hyperglycemia reversion in 70% of diabetic mice (responders), improved the number and size of pancreatic islets and increased circulating-insulin levels." (PMID 25884215, 2015). "Type 1 diabetes (T1D) is a chronic autoimmune disease characterized by hyperglycemia due to progressive immune-mediated destruction of insulin-producing pancreatic islet β cells." (PMID 26579520, 2015). "In conclusion, the present study in pancreatic islets of GK rats suggests defects in PKCα, PKCε, and p-PKCζ expressions secondary to hyperglycaemia, since the expression pattern was restored after insulin treatment." (PMID 26398746, 2015).
Hyperglycemia (continued). "Hydroxycinnamic acid derivative p-methoxycinnamic acid promoted glycolysis, reduced gluconeogenesis in the liver of diabetic rats, and increased the secretion of insulin to reduce hyperglycemia in streptozotocin (STZ)-induced diabetic rats." (PMID 26633482, 2015). "The pro-insulin cluster contained only one SNP, which was found to have pleiotropic effects; and the hyperglycemia cluster contains only two SNPs, one of which was found to have pleiotropic effects." (PMID 26017687, 2015). "The cornerstones of prevention are aggressive treatment of sepsis, early mobilization, preventing hyperglycemia with insulin, and avoiding the use parenteral nutrition during the first week of critical illness." (PMID 26242743, 2015). "This insulin schedule has been satisfactorily used by patients for about 3 years, and no specific complications, such as frequent catheter clogging or severe hyperglycemia, have occurred." (PMID 25614824, 2015). "β-cell dysfunction and death are processes that are also connected to various levels of ER stress, particularly because hyperglycaemia requires increased “work power” by the islets that need to produce higher amounts of protein (insulin)." (PMID 26257839, 2015). "Basal bolus insulin therapy based on BG results is safe and efficacious in the management of inpatient hyperglycemia." (PMID 26697118, 2015). "Flies fed a lipid-rich diet presented with increased fat storage, systemic activation of JAK-STAT signaling, reduced insulin sensitivity, hyperglycemia, and a shorter lifespan." (PMID 25601202, 2015). "For example, mice with β-cell-specific deletion of Xbp-1 displayed hyperglycemia and glucose intolerance resulting from decreased insulin secretion." (PMID 26613076, 2015). "For example, hypoglycemia increases glucagon levels and triggers whole-body proteolysis, while hyperglycemia increases insulin levels and counteracts the proteolytic effect of glucagon." (PMID 26682277, 2015). "STZ induces hyperglycemia by destroying pancreatic β-cells and consequently reducing insulin production." (PMID 25763088, 2015). "The reversal of hyperglycemia and hyperinsulinemia cannot be accounted for by the improvement in muscle insulin resistance alone." (PMID 26172834, 2015). "F12016 administration not only prevented rising hyperglycemia and improved insulin sensitivity similar to rosiglitazone, but also suppressed weight gain compared with vehicle or rosiglitazone." (PMID 25827822, 2015). "Typically, WFS necessitates insulin treatment similar to type 1 diabetes (T1D), but the mechanism of beta cell mass reduction leading to hyperglycemia is different." (PMID 25916214, 2015). "Liver is a main metabolic organ for glucose; in the fed state, which is stimulated by insulin to take more glucose from the blood and synthesize glycogen, thus reducing the postprandial hyperglycemia." (PMID 26198246, 2015). "DNJ has been recognized as α-Glycosidase inhibitor for the past decades; however, our present study provided strong evidence that DNJ alleviates hyperglycemia by improving insulin sensitivity in skeletal muscle of db/db mice." (PMID 26690098, 2015). "After hyperglycemia was confirmed (on day 5 after the injection), an insulin pellet was implanted s.c. and the animals were continuously monitored for 6 or 11 weeks." (PMID 26656101, 2015). "The after-effects of a long-lasting high-fat diet were shown in rodents and include increasing levels of insulin, insulin resistance and mild hyperglycemia." (PMID 25943490, 2015). "The third possible explanation for hyperglycemia is decreased insulin-dependent glucose uptake into peripheral tissues." (PMID 26466345, 2015). "At peak stress, the combination of pancreatic β1-stimulation from dobutamine and hyperglycemia led to a marked potentiation of insulin release, increasing further the differences between insulin and FFA." (PMID 26253538, 2015).
Hyperglycemia (continued). "The relationship between hyperglycemia and hospital outcomes is well-established and major consensus recommends that insulin therapy should be prescribed for all patients with hyperglycemia, preferentially with basal-bolus regimen." (PMID 26697118, 2015). "It is characterized by hyperglycemia resulting from defects in insulin secretion, insulin insensitivity, or both." (PMID 26788368, 2015). "Thereafter, sustained hyperglycemia leads to glucotoxicity, which further worsens insulin sensitivity and secretion." (PMID 25615826, 2015). "When IR becomes more severe and glucose homeostasis cannot be maintained despite increased insulin levels, mild hyperglycemia sets in and a prediabetic state begins to manifest." (PMID 25961014, 2015). "In rodent models of T1D, transplantation of MSCs reverted hyperglycemia, recovered pancreatic islets, increased insulin production and promoted beneficial immunologic changes." (PMID 25884215, 2015). "Knockdown of FMO3 in insulin-resistant mice suppresses FoxO1, a central node for metabolic control, and entirely prevents the development of hyperglycaemia, hyperlipidemia and atherosclerosis." (PMID 25849138, 2015). "The present improved insulin sensitivity and antihypertensive action of GO are consequences of reduced hyperglycemia and PPAR-γ activation to suppress proinflammatory mediators, RAGE, and HbA1c." (PMID 25679220, 2015). "Control of hyperglycemia with luseogliflozin or insulin significantly reduced the degree of hyperfiltration compared to the rats treated with vehicle." (PMID 26169541, 2015). "Inhibition of glucose uptake by muscle and fat, and decreased insulin production and secretion, further promote hyperglycaemia." (PMID 26550039, 2015). "It would also be of interest to examine integration between dynamic measures of insulin sensitivity, postprandial hyperglycemia, and EMPs on the morning following exercise but our measurements were limited to fasting samples only." (PMID 25710559, 2015). "The results demonstrate the ability of multiple infusions of MSCs to promote prolonged decrease in hyperglycemia and apoptosis in pancreatic islets and increase in insulin sensitivity in HFD fed mice." (PMID 25923733, 2015). "Hyperglycaemia increases oxidative stress, which contributes to the impairment of insulin action and insulin secretion." (PMID 27486368, 2015). "Within obese populations, upper body fat distribution, increased liver fat content, hypertension, hyperglycemia and dyslipidemia (known collectively as the metabolic syndrome), have been shown to confer lower insulin clearance." (PMID 26297500, 2015). "Common adverse events related to MK-2206 included rash, an elevated insulin c-peptide level, stomatitis, pyrexia, eosinophilia, leukopenia, and hyperglycemia." (PMID 26104654, 2015). "As ZDF rats age, reduced plasma insulin correlates with the progression of hyperglycemia to levels beyond those observed in younger hyperinsulemic rats and appears related to β-cell apoptosis, similar to human type-2 DM." (PMID 25996498, 2015). "Although we did not determine glucose concentrations in the blood of females during As exposure, hyperglycemia, high levels of insulin, and impaired glucose tolerance in pregnant mice exposed to As have been reported." (PMID 26339590, 2015). "Moreover, if our study participants represent a more insulin resistant phenotype they may simply be more susceptible to environmental elements (e.g. hypercaloric diet and sedentary lifestyle) which leads to hyperglycemia and hence HbA1c>7% which may precede β-cell dysfunction." (PMID 25157406, 2014). "These periods were usually preceded by intervals of hyperglycaemia and ketosis that resulted in repeated admission to the intensive care unit, where the patient was managed with i.v. insulin." (PMID 24711924, 2014).
Hyperglycemia (continued). "Stress hyperglycaemia is common in acute myocardial infarction, whereas increased catecholamine levels result in decreased insulin secretion and increased insulin resistance." (PMID 25013458, 2014). "Insulin treatment remains the main therapy for the control of hyperglycemia in diabetic patients with ESRD requiring hemodialysis, but it sometimes induces severe hypoglycemia." (PMID 25526642, 2014). "Along with hyperglycemia, plasma insulin levels in control group decreased gradually after day 21 of treatment with aging, suggesting the exhaustion of pancreatic beta cells." (PMID 24895641, 2014). "Integrating miR-182 tissue expression profile, target genes, and copy number in blood reveals that miR-182 plays a key role in crucial genes modulation, such as FOXO1 and BHLHE22, which leads to potential hyperglycemia and modulates the insulin secretion." (PMID 25530976, 2014). "Studies in multiple mouse strains have shown that rapa has variable effects on glucose homeostasis and insulin sensitivity, and studies in humans have indicated that hyperglycemia is a side effect in roughly 10% of patients." (PMID 25473963, 2014). "A ‘step up’ approach was followed depending on severity of hyperglycaemia, whereby diet and exercise modification was advised and metformin and/or insulin added accordingly." (PMID 25199524, 2014). "While BG in VTD did not significantly change for one week after vanadium withdrawal, in ITD, the re-occurrence of hyperglycemia (BG>400 mg//dL) was observed 48 h after cessation of NPH insulin." (PMID 24842144, 2014). "Mothers who develop GDM are usually treated by dietetic measures and/or insulin therapy to prevent fetal hyperglycemia and hyperinsulinism." (PMID 25187623, 2014). "The GLUT4 transporter, a signaling molecule that affects myocardial function, is downregulated with chronic hyperglycemia, and is upregulated with administration of insulin." (PMID 24886864, 2014). "No major adverse events such as ketoacidosis were seen during the course of the present study, but there have been cases in Japan of diabetic ketoacidosis or hyperglycemia following a switch from insulin therapy to lira." (PMID 24578756, 2014). "An indirect consequence of reducing postprandial hyperglycemia with acarbose is an increase of insulin sensitivity." (PMID 24742256, 2014). "Tyrberg and colleagues showed that an intravenous dose of 1 g/kg fructose was able to elicit an insulin response prior to measurable hyperglycemia in wild type mice." (PMID 25100436, 2014). "This is likely due to the increased neurohormonal activity associated with polytrauma itself which will further increase cortisol levels and, therefore, hyperglycemia and insulin requirements." (PMID 25026864, 2014). "FGF21 is a unique member of the FGF family and plays a significant role in regulating glucose and lipid metabolism, including stimulating glucose uptake insulin-independently, improving hyperglycemia and dyslipidemia." (PMID 24895642, 2014). "Although hyperglycemia can be improved by insulin administration, exogenous insulin injection cannot successfully mimic the insulin secretion from normal β cells, which keeps blood glucose levels within the normal range all the time." (PMID 25364717, 2014). "Accordingly, we have proposed a regimen consisting of a two-step administration of postprandial hypoglycemic agents, namely an alpha-glucosidase inhibitor and a glinide, to basal insulin therapy to target postprandial hyperglycemia." (PMID 24684803, 2014). "C57BL/KsJ-db/db mice are spontaneously hyperinsulinemia, hyperglycaemia, and insulin resistant after 6–8 weeks of age, which are commonly and extensively used for the investigation of T2DM." (PMID 25431772, 2014). "So, we have phenotypically established two groups of obese BATIRKO mice as characterized by their plasma insulin levels, pancreatic islet area, islet insulin content, and also by their glucose tolerance curves and fasting hyperglycemia." (PMID 25077985, 2014).
Hyperglycemia (continued). "After resolution of diabetic ketoacidosis and hyperglycemia, exogenous insulin can be safely discontinued in a portion of KPDM patients, and these subjects maintain good glycemic control with diet or with oral hypoglycemic agents." (PMID 25275325, 2014). "The cell clusters expressed a broad gene profile related to pancreatic islet cells, released insulin and c-peptide in a glucose concentration-dependent manner, and normalized hyperglycemia of streptozocin-induced mice for at least 80 days following xenograft." (PMID 24887638, 2014). "Unexpectedly, diabetic ketoacidosis and hyperglycemia occurring as a result of switching from insulin therapy to lira were reported at the time of lira’s introduction to Japan." (PMID 24578756, 2014). "Those with fasting hyperglycemia also gained 2.0 kg more weight after insulin initiation (p = 0.020, after adjustment for baseline BMI, p = 0.035)." (PMID 23880900, 2014). "Repeated (14 days) administration of the methanol extract alleviated hyperglycemia and simultaneously increased plasma insulin levels in the streptozitocin-induced diabetic rats compared with those of the control diabetic rat." (PMID 24993916, 2014). "The 24-hour data suggest that insulin rescue and reversal of hyperglycemia significantly increased complement activation and anaphylatoxin generation in response to S. aureus infection." (PMID 25610878, 2014). "A comprehensive review of published literatures on the effects of hyperglycemia and insulin on innate immunity in critical illness was conducted." (PMID 24899891, 2014). "In line with fasting hyperglycemia and hyperinsulinemia B12R offspring had higher (than controls) AUC for glucose and insulin during the oral glucose tolerance test, at 12 months of age but not earlier." (PMID 25398136, 2014). "Hyperglycemia is a state of metabolic dysregulation due to an imbalance between insulin production and insulin sensitivity in the target tissues." (PMID 24628829, 2014). "Hyperglycemia was reversed in streptozotocin-treated diabetic mice when embryonic stem cell (ESC)-derived insulin-producing cells were transplanted into these mice." (PMID 25364723, 2014). "Hyperglycemia alters glucose metabolism within β-cells and interstitial conditions around β-cells, including elevated osmolarity and increased concentrations of insulin and ATP released from overstimulated β-cells." (PMID 24704640, 2014). "We observed that Pdx1tTA/+ mice exhibit previously reported MODY4 symptoms including hyperglycemia, reduced plasma insulin, impaired glucose tolerance, and aberrant localization of alpha cells to the core of the islet." (PMID 25144761, 2014). "The Akita mutation causes beta‐cell failure as a result of protein aggregate‐induced endoplasmic reticulum stress due to improper folding of proinsulin resulting in reduced insulin production and hyperglycemia." (PMID 25428948, 2014). "In STZ-induced diabetic mice, it has been shown that genistein improved hyperglycemia, glucose tolerance and circulating insulin concentrations by increasing islet β cell proliferation, β cell mass and survival." (PMID 25421534, 2014). "Previous studies revealed that the insulin-mimetic actions of vanadium in type 1 diabetic patients or insulin-dependent diabetic rats needed a minimum level of insulin to overcome hyperglycemia." (PMID 24842144, 2014). "Hyperglycemia leads to an excessive peripheral utilization of insulin, resulting in reduced insulin transport to the brain." (PMID 24409116, 2014). "In summary, this is the first report to our knowledge that dietary supplementation of baicalein significantly ameliorated hyperglycemia and increased blood insulin levels, concomitant with improved functional islet mass, in obese diabetic mice." (PMID 25147566, 2014). "Ferrets exhibited rapid decreases in insulin levels in response to hypoglycemia that followed hyperglycemia, similar to but perhaps more rapid and profound than that observed in similar studies in humans." (PMID 24594704, 2014).